MIR99B (microRNA 99b)
Synonyms: hsa-mir-99b; MIRN99B; mir-99b
Gene: MicroRNA gene on chromosome 19 (51,692,612 to 51,692,681, forward strand). Ensembl gene ENSG00000207550.
Gene Ontology:
Biological process: miRNA-mediated post-transcriptional gene silencing
Cellular component: RISC complex
Homologues: Orthologues: chimpanzee ptr-mir-99b (100% identical), macaque MIR99B (100% identical), mouse Mir99b (100% identical), pig MIR99B (100% identical), rat Mir99b (100% identical), guinea pig MIR99B (99% identical), dog MIR99B (83% identical), tropical clawed frog xtr-mir-100 (70% identical). Paralogues in human: MIR99A (71% identical), MIR100 (66% identical), MIR125A (53% identical), MIR10A (50% identical), MIR125B2 (50% identical), MIR10B (47% identical), MIR125B1 (44% identical).